CCND1 (cyclin D1)
Diseases named in the same sentence as CCND1 in open-access papers (continued):
Sharing a sentence is not in itself a finding about the gene and the disease.
tumor (continued). "It is clear that CCND1 encodes CyclinD1 protein and the new discoveries of CCND1 on tumor metastasis are novel and attractive." (PMID 25823925, 2015). "Over-expression of Cyclin D1 oncogene can release cell from their normal cell cycle control and causes transformation to neoplasia." (PMID 25888009, 2015). "The expression of Cyclin D1 was positively associated with tumor size (p = 0.031), distant metastasis (p = 0.024) and poor survival (p = 0.034)." (PMID 25823925, 2015). "Ioachim found that the overexpression of Cyclin D1 was significantly associated with tumor stage and lymph node involvement in CRC." (PMID 25202365, 2014). "In a study with TGFBI null mice, loss of TGFBI promoted cell proliferation via aberrant activation of the CREB-cyclin D1 pathway and predisposed mice to spontaneous tumor development." (PMID 25369402, 2014). "Joint detection provided a worse prognostic value in CRC, indicating that loss of PTEN exhibited a synergistic role with Cyclin D1-positive expression in tumor progression." (PMID 25202365, 2014). "Activated Stat3 has been shown to protect tumour cells from apoptosis and promote cell proliferation by regulating genes coding anti-apoptotic and proliferation-associated proteins such as Bcl, Ccnd1 and c-Myc." (PMID 25297811, 2014). "When the data was pooled, there were significant association between high cyclin D1 expression and the clinicopathological parameters except tumor size and histology." (PMID 24728073, 2014). "Our results indicated that increased expression of MIF and cyclin D1 was significantly associated with tumor size." (PMID 25015194, 2014). "The expression of cyclin D1 was significantly associated with tumor stage, histological grade, tumor differentiation, and mitotic count." (PMID 24019980, 2013). "Using multi-factor Cox proportional hazards regression models to analyze TNM stage, lymph metastasis, tumor classification, tumor location, cyclin D1 and Ang-2, the tumor classification and cyclinD1 are associated with the survival rate." (PMID 24223635, 2013). "The hyperphosphorylation of RB inactivates its role as a tumor suppressor, and thus mutations that target either CCND1 or RB1 are thus important for proliferation in cancer." (PMID 23717195, 2013). "The E3 ligase FBXO31-SCF has previously been implicated in cell cycle regulation as it emerged as a tumor suppressor and regulator of DNA repair by degrading cyclin D1." (PMID 23469015, 2013). "The expression of β-catenin was significantly associated with histological grade, tumor differentiation, mitotic count, and cyclin D1 expression." (PMID 24019980, 2013). "In this regard, the expression of a spliced isoform of eIF4H was shown to be strictly associated with the tumour behaviour and increased translation rate of peculiarly structured 5′cap mRNAs, including those of proliferative functions, such as cyclin D1." (PMID 23776612, 2013). "High BMI was associated with cyclin D1 positive (ptrend =0.019) and p 53 positive (ptrend =0.023) tumours, and borderline significantly associated with beta-catenin positive CRC (ptrend =0.050)." (PMID 24256736, 2013). "Once cyclin D1 mutates or expresses excessively during the process of cell proliferation, cyclin D1 promotes the induction and development of a tumor." (PMID 24223635, 2013). "As regards cyclin D1 expression, the results from the present study demonstrate a significant association between a high height and weight and risk of cyclin D1 positive tumours in women." (PMID 24256736, 2013).
tumor (continued). "Cyclin D1 overexpression is considered to be an important factor in the promotion of tumor occurrence and development, where it is also associated with reduced response to growth factors." (PMID 23693134, 2013). "The expression of Cyclin D1 was associated with tumor size of TSCC (P = 0.023), whereas the expression of Bcl-2 was not statistically significantly associated with any of the clinicopathologic parameters." (PMID 23451060, 2013). "Immunohistochemical investigation of RCC tissue samples demonstrated cyclin D1 and D3 expression to be closely associated with tumor size, stage and grade." (PMID 23372654, 2013). "In a previous study on tumours from this cohort, elevated cyclin D1 expression was found to associate with a prolonged survival, in particular in male patients." (PMID 23337059, 2013). "NFkB regulates the expression of numerous antiapoptotic proteins associated with tumor survival (bcl-xl, bcl-2, XIAP, c-FLIP, IAP-1, IAP-2, and survivin), as well as genes associated with tumor progression (cyclin D1, c-myc and COX-2)." (PMID 23145063, 2012). "CGK062 repressed the expression of its target genes, including those encoding cyclin D1, c-myc and axin-2, thereby suppressing tumor growth in vitro and in vivo." (PMID 23071615, 2012). "Even when adjusting for the effects of tumour size, nodal status, grade (central) and Ki67 expression, amplification of CCND1 was significantly associated with an increased risk of recurrence (HR = 1.61; 95% CI, 1.08 to 2.41; P = 0.03)." (PMID 22475046, 2012). "USP2a, which forms a complex with MDM2, the MDM2 homologue MDMX, FASN (fatty acid synthase), cyclin D1 and Aurora A, is positively linked to tumor progression." (PMID 23236372, 2012). "It is likely that the overexpression of mRNA of cMYC and CCND1 in non neoplastic cells of PHTS patients puts them at hight risk of developing these types of tumours." (PMID 22520842, 2012). "Overexpression of cyclin D1 protein was significantly associated with lymph node metastasis, tumor cell differentiation and tumor stage in Taiwanese OSCC." (PMID 22336657, 2012). "In humans, CCND1 is frequently overexpressed in a variety of tumor types and is associated with carcinogenesis and metastasis." (PMID 23236518, 2012). "Overexpression of cyclin D1 is frequently associated with tumorigenesis, angiogenesis, and tumor growth." (PMID 22359572, 2012). "Amplification of CCND1 was observed in 8.7% of the tumours and was associated with increased risk of disease recurrence (hazard ratio = 1.61; 95% confidence interval, 1.08 to 2.41) after adjustment for other clinicopathological parameters." (PMID 22475046, 2012). "IgG expression was associated with tumor differentiation, pTNM stage, lymph node involvement and inflammatory infiltration and positively correlated with the expressions of Cyclin D1, NF-κB and PCNA." (PMID 23133595, 2012). "Patients with tumours exhibiting low Ki67 expression in association with 1 to 100% cyclin D1-positive nuclei (high) were associated with a considerably lower risk of recurrence (P < 0.001) compared with the other subgroups." (PMID 22475046, 2012). "Survival plots showed that patients exhibiting CCND1-amplified tumours had an increased risk of recurrence compared with patients showing nonamplified tumours (HR = 2.04; 95% CI, 1.37 to 3.03; χ12 = 10.51; P < 0.001, univariate)." (PMID 22475046, 2012). "Ras association domain family 1 isoform A is a tumor suppressor that negatively regulates cell proliferation by inhibiting cyclin D1 protein accumulation through posttranscriptional mechanisms." (PMID 23144874, 2012). "RASSF1A hyperM has previously been inversely associated with cyclin D1 expression and tumor cell proliferation." (PMID 23144874, 2012). "A similar trend was noted for ID1, where in all patients low expression of the gene was associated with a shortest RFS, but in the CCND1 low ER-positive subgroup of tumours, a positive correlation was found." (PMID 21955753, 2011).
tumor (continued). "The results from this large cohort study show that tumor-specific cyclin D1 expression is strongly associated with a prolonged survival from CRC in men but not women." (PMID 21888663, 2011). "TheMEN1 gene is mutated in about 30% of theparathyroid tumours and the protooncogene CCND1 isimplicated in parathyroid neoplasia by rearrangements, leading to anoverexpression of CCND1 protein in parathyroid cells." (PMID 22567348, 2011). "Nuclear Kaiso is known to repress various tumor-associated β-catenin target genes, such as Ccnd1, which encodes cyclin D1." (PMID 20169156, 2010). "Tumor cells with overexpression of Cyclin D1 and c-myc are associated with favorable outcomes while overexpression of p21, p57, and PCNA are linked with adverse outcomes." (PMID 20152033, 2010). "This suggests that deregulated cyclin D1 expression can contribute to the invasive and metastatic potential of a tumour, since mtDNA mutations can lead to development of metastases by overproduction of reactive oxygen species (ROS)." (PMID 21176227, 2010). "Cyclin D1 is a cell-cycle regulatory protein and its upregulation has been associated with increased proliferation and poor clinical outcome in various tumours." (PMID 20485284, 2010). "Intratumoral injection of anti-Wnt-1 antibody suppressed in vivo tumor growth in a Huh7 xenograft model, which was also associated with apoptosis and reduced c-Myc, cyclin D1, and survivin expressions." (PMID 19778454, 2009). "Cyclin D1 promotes cell-cycle progression and its overexpression is known to correlate with the early onset of cancer and risk of tumor progression and metastasis." (PMID 19523245, 2009). "Cyclin D1, encoded by the Bcl-1 gene, is a putative protooncogene, and previous studies have shown that both YB-1 and cyclin D1 are upregulated in many neoplasms." (PMID 20414334, 2009). "As one example, Guggulsterone, a plant-derived drug, caused cell-cycle arrest in S-phase by the suppression of cyclin D1 and cdc2 and increased cyclin-dependent kinase inhibitor p21 and p27 expression in a wide variety of human tumor cell types." (PMID 18509533, 2008). "While cyclin D1 overexpression occurs frequently in human cancer and is considered a causative factor in many tumor types, simple over-expression of wild type cyclin D1 is insufficient to drive neoplastic transformation." (PMID 18764945, 2008). "In accordance with endometrial cancer studies, recently identified cyclin D1 mutations in esophageal cancer and tumor-derived cell lines also disrupt Thr-286 phosphorylation." (PMID 18764945, 2008). "Tumor-specific alternative splicing produces a truncated transcript lacking exon 5, the region encoding the C-terminal Thr-286; this cyclin D1 transcript b (D1b) produces a constitutively nuclear protein refractory to proteasomal degradation." (PMID 18764945, 2008). "Low energy intake was associated with nucleus grade 3 tumours as well as overexpression of cyclin D1 and high proliferation." (PMID 17254341, 2007). "Increased cyclin D1 was significantly associated with tumor size (p = 0.003) and FIGO stage (p = 0.008) whereas, increased cyclin E expression was significantly associated with tumor size (p = 0.001)." (PMID 17521451, 2007). "Low intake of SFA was relatively more common in tumours of nucleus grade 3 as well as in tumours of high proliferation and with overexpression of cyclin D1, whereas overexpression of cyclin E was associated with high SFA intake." (PMID 17254341, 2007). "Although intragenic somatic mutation of cyclin D1 in human disease is rare, cyclin D1 gene translocation, amplification and/or overexpression are frequent events in selected tumor types." (PMID 16863592, 2006). "The location of the alternate splicing event generated significant interest, as the splice donor site encompasses a known polymorphism of cyclin D1 that has been associated with increased cancer risk and/or poor prognosis in a multitude of tumor types." (PMID 16863592, 2006).
tumor (continued). "The pro-proliferative function of cyclin D1 is mediated through its ability to regulate the cell cycle machinery, and excessive cyclin D1 expression and/or activity is a hallmark of several tumor types." (PMID 16863592, 2006). "Tumours overexpressing cyclin D1 were further associated with a slightly improved survival, and in summary we show that randomised treatment trials including an untreated control arm are necessary in order to differ predictive and prognostic information." (PMID 15138475, 2004). "Aberrations in cyclin D1 and p27 were further associated with nuclear grade, tumour size, and patient survival." (PMID 12778072, 2003). "One simple explanation is that CCND1 overexpression is associated with well-differentiated, oestrogen receptor-positive tumours (which are known to have a more favourable prognosis and a respond better to anti-oestrogen therapy." (PMID 11870541, 2002). "Cyclin D1 overexpression was associated with a poorly differentiated histology (P = 0.04), less lymphocytic infiltration of the tumour (P = 0.02) and a reduction in local relapse rate (P = 0.01)." (PMID 8562333, 1996). "Similarly, the association between cyclin D1 expression and tumor grade was found to be statistically significant (p = 0.001)." (PMID 41541922, 2025). "Additionally, miR-93-5p has been implicated in the regulation of carcinogenesis and tumor immunity by targeting the PD-L1/CCND1 axis, with potential use as a biomarker for patient risk stratification and treatment." (PMID 39412136, 2025). "Cyclin D1 has been implicated in the tumorigenesis of several neoplasms when overexpressed." (PMID 40422510, 2025). "The effect of IL-22 on tumor growth was investigated by using an in vivo model of HCC: a significant increase in tumor volume was associated with enhanced phosphorylation of STAT3 as well as upregulation of cyclin D1." (PMID 40806452, 2025). "Cyclin D1 overexpression may enhance tumor proliferation but, at the same time, render tumor cells more susceptible to cell cycle-targeted agents such as TKIs, thereby improving treatment responsiveness and survival outcomes." (PMID 41189865, 2025). "Elevated Cyclin-d1 expression in CSCs is linked to aggressive tumor behavior and poor prognosis." (PMID 40011711, 2025). "Cyclin D1 up-regulation is linked to higher tumor stage and lymph node metastasis in HNSCC." (PMID 39892781, 2025). "High cyclin D1 was also associated with increased circulating tumor cells (CTCs) (P < 0.001)." (PMID 40674249, 2025). "For example, rearrangements involving the CCND1 gene, which encodes cyclin D1, a key regulator of the G1-S phase transition in the cell cycle, can result in its overexpression, promoting cell cycle progression and tumor proliferation." (PMID 40427514, 2025). "Overexpression of cyclin D1 may cause cycle disorders, DNA damage, and mutant cell replication and division, leading to tumor development." (PMID 40308769, 2025). "Furthermore, CCND1 overexpression in HNSC is significantly associated with higher tumor stage and lymph node metastasis, suggesting its potential as a prognostic marker." (PMID 39188436, 2024). "By contrast, luminal cluster 2 was enriched in a proliferative gene signature (Mki67, Ccnb2, Cdk1, Ccnb1 and Ccnd1), which may be associated with cycling progenitors fuelling tumour growth." (PMID 38238426, 2024). "A pan-cancer analysis of CCND1 may discover tumor diagnostic and prognostic biomarkers and the distinctive and similar characteristics that distinguish genes among multiple tumors." (PMID 39188436, 2024).
tumor (continued). "Moreover, UGZ–1004 exposure led to the downregulation of genes associated with tumor development, including CCND1 and TFDP1, mitigating potential tumorigenic risks." (PMID 39337305, 2024). "Furthermore, he has studied histone deacetylase 8 (HDAC8), BRCA1, YWHAE-FAME22 rearrangement, Cyclin D1, tumor cell necrosis (TCN), and BCRO as diagnostic markers for uLMS." (PMID 38410101, 2024). "Stationary markers, such as the protein expression of Signal Transducers and Activators of Transcription 3 (STAT3) and Cyclin D1, or whole cell populations within the tumor, particularly tumor-infiltrating leukocytes, were reported to be associated with survival outcomes." (PMID 38392590, 2024). "Conversely, Per2 deficiency disrupts tumour suppressors (Ccnd1 and c-Myc), promoting tumour growth." (PMID 39566400, 2024). "However, we did not reveal statistically significant associations between SNPs in CCND1 and tumour expression of CCND1 in eQTL analysis." (PMID 38994482, 2023). "We believe that this finding may depend on some emerging functions of cyclin D1 associated with invasion and thus with the metastatic capacity of a tumor." (PMID 37569265, 2023). "Ligands of the WNT canonical pathway, such as WNT1 and WNT10A, are associated with tumor progression, poor prognosis, and tumor invasiveness in ccRCC patients by oncogene activation, such as c-Myc and cyclin D1." (PMID 36910160, 2023). "This amplification could affect CCND1 tumour expression, which makes it more difficult to compute direct associations between SNP variation and CCND1 expression in eQTL analysis." (PMID 38994482, 2023). "The SNP with the strongest association in CCND1, rs655089, is located upstream of CCND1 and could act on CCND1 expression in tumour tissue through transcription factor binding." (PMID 38994482, 2023). "Moreover, the tumor recurrence and the cyclin D1 rebound were associated with hyperactivation of MAPK pathway." (PMID 36387174, 2022). "In addition, the KIT mutation co-occurred with CCND1 amplification in 0.33% (1/302), 0.82% (3/367), and 0.57% (2/350) of tumor samples in the Geneplus, TCGA, and MSKCC cohorts, respectively." (PMID 35844619, 2022). "Moreover, in this group, overexpression was found in several tumor oncogenic genes (such as CCND1, MDM2, MDM4, and DNMT3A), which positively associated with hyperprogression, which led to ICB-related high progression of the disease." (PMID 35909893, 2022). "It causes CCND1 upregulation, leading to kinase activation and tumor cell proliferation." (PMID 35982976, 2022). "The effect of IFITM1 on tumor progression is often linked to altered levels of β-catenin, cyclin D1 and c-myc, which might account for the roles of IFITM1 in cancer cell migration, metastatic potential and proliferation." (PMID 36466909, 2022). "Cyclin D1 is upregulated or mutated in various tumor types, which alters cell proliferation." (PMID 35669244, 2022). "Cyclin D1-positive expression was significantly associated with tumor size (P = 0.02, P < 0.05)." (PMID 35242498, 2022). "This hypothesis was strengthened recently when a meta-analysis of over 1000 patients identified amplification of CCND1 (encoding Cyclin D1) as one of the strongest tumor-intrinsic predictors of resistance to ICI30." (PMID 35444175, 2022). "Furthermore, they can cause cell cycle arrest (e.g., by downregulation of Cyclin D1), and inhibit tumor growth through the upregulation of tumor and metastasis suppressors." (PMID 33466433, 2021). "Furthermore, upregulation of cyclin D1 in HCCs has been noted to be associated with aggressive tumor forms." (PMID 34298825, 2021). "If the amplification of CCND1 is associated with overexpression of the corresponding protein, it might result in upregulation of the cell cycle and tumor aggressiveness." (PMID 33466719, 2021). "In addition, previous studies have proved that p21 and cyclin-D1 are the Wnt targets associated with the proliferation of tumor cells." (PMID 34722259, 2021).